SPTSSB (serine palmitoyltransferase small subunit B)
Description:
Component of the serine palmitoyltransferase multisubunit enzyme (SPT) that catalyzes the initial and rate-limiting step in sphingolipid biosynthesis by condensing L-serine and activated acyl-CoA (most commonly palmitoyl-CoA) to form long-chain bases. The SPT complex is composed of SPTLC1, SPTLC2 or SPTLC3 and SPTSSA or SPTSSB. Within this complex, the heterodimer consisting of SPTLC1 and SPTLC2/SPTLC3 forms the catalytic core. Within the SPT complex, SPTSSB stimulates the catalytic activity and plays a role in substrate specificity. SPT complexes with this subunit showing a preference for longer acyl-CoAs. The SPTLC1-SPTLC2-SPTSSB complex shows a strong preference for C18-CoA substrate, while the SPTLC1-SPTLC3-SPTSSB isozyme displays an ability to use a broader range of acyl-CoAs, without apparent preference.
Synonyms: ssSPTb; ADMP; C3orf57
Tractability: Antibody: UniProt predicts a signal peptide or a membrane-spanning region.
Gene: Protein-coding gene on chromosome 3 (161,344,798 to 161,372,880, reverse strand). Ensembl gene ENSG00000196542.
Subcellular location: Endoplasmic reticulum membrane
Pathways (Reactome):
Metabolism: Sphingolipid de novo biosynthesis
Gene Ontology:
Molecular function: protein binding; serine C-palmitoyltransferase activity
Biological process: sphingosine biosynthetic process; ceramide biosynthetic process; endoplasmic reticulum organization; sphingolipid biosynthetic process; sphingolipid metabolic process
Cellular component: serine palmitoyltransferase complex; endoplasmic reticulum membrane
Genetic constraint (gnomAD): Loss-of-function variants: 4 observed, 5.65 expected, observed/expected ratio (o/e) 0.71, 90% interval 0.35 to 1.56. That is too few expected variants to judge how well the gene tolerates losing a copy. Missense variants: 40 observed, 44.12 expected, observed/expected ratio (o/e) 0.91, 90% interval 0.7 to 1.18. Synonymous variants: 13 observed, 15.52 expected, observed/expected ratio (o/e) 0.84, 90% interval 0.54 to 1.33.
Homologues: Orthologues: chimpanzee SPTSSB (100% identical), rabbit SPTSSB (96% identical), guinea pig SPTSSB (87% identical), pig SPTSSB (87% identical), mouse Sptssb (86% identical), rat Sptssb (86% identical), tropical clawed frog sptssb (62% identical), zebrafish sptssb (55% identical), Drosophila melanogaster CG34194 (24% identical), Drosophila melanogaster CG34293 (22% identical). Paralogues in human: SPTSSA (38% identical).
Diseases named in the same sentence as SPTSSB in open-access papers:
SPTSSB is named in the same sentence as 6 diseases in open-access papers, as found by Europe PMC text mining. Sharing a sentence is not in itself a finding about the gene and the disease. The quoted sentences say what the papers report.
diabetes (1 paper, 2022). "SGMS1, SGPL1, and SPTSSB showed increased expression only in transplanted islets with recurrent diabetes (Tx)." (PMID 36589856, 2022).
SPTSSB also shares sentences with these, for which no sentence is quoted: breast carcinoma (1 paper); cancer (1); gastric cancer (1); Parkinson (1); tumour (1).